LEP (leptin)
Diseases named in the same sentence as LEP in open-access papers (continued):
Sharing a sentence is not in itself a finding about the gene and the disease.
pancreatic cancer (continued). "Overexpression of leptin in an orthotopic model of human pancreatic cancer promotes tumor growth and lymph node metastasis, indicating that leptin is a key factor for PDAC." (PMID 33101198, 2020). "The circulating leptin concentration is higher in patients with breast, gastric, and endometrial cancer, but it is lower in pancreatic cancer." (PMID 30186533, 2018). "Chemokine MCP1 and a proinflammatory biomarker score including MCP1, leptin, and PAI1 were associated with increased risk of incident pancreatic cancer among lean women." (PMID 29573228, 2018). "In pancreatic cancer, leptin induced cancer cell migration/invasion and metastasis in orthotopic model, and the simultaneously increased leptin receptor and MMP13 production displayed the positive correlation with patient's TNM stages." (PMID 29682217, 2018). "Effect modification by BMI of the association between pancreatic cancer risk and the proinflammatory composite biomarker comprising MCP1, PAI1, and leptin was also seen." (PMID 29573228, 2018). "We and others have shown that leptin promotes the proliferation and an invasive potential of pancreatic cancer cells through STAT3 mediated signaling." (PMID 29156726, 2017). "In this study we provide the first evidence that both adiponectin and AdipoRon inhibit pancreatic tumor growth and overcome leptin mediated mitogenic signaling." (PMID 29156726, 2017). "The real correlation between the circulating leptin and pancreatic cancer still requires data from prospective cohort studies." (PMID 25948792, 2015). "We then tested the effect of the JAK2 inhibitor AG490 on the leptin-induced enhancement of the migration and invasion of the pancreatic cancer cells." (PMID 25948792, 2015). "Due to the increased pAKT and pSTAT3 observed in our studies with leptin treatments, we were interested to determine how leptin stimulation altered the proliferation of pancreatic cancer cell lines." (PMID 25919692, 2015). "In conclusion, we demonstrate that leptin is partially responsible for the growth of pancreatic tumors in obese mice." (PMID 25919692, 2015). "From the existing results, it appears that patients with pancreatic cancer had a lower concentration of circulating leptin compared to the controls." (PMID 25948792, 2015). "The local increase of leptin in the pancreas and the ability of leptin to induce proliferation of cancer cells, warranted a study to determine the contribution of leptin to pancreatic tumor growth in this murine model." (PMID 25919692, 2015). "The role of leptin and leptin receptor signaling in pancreatic cancer development and progression remains ill defined." (PMID 25919692, 2015). "Taken together, this study provides the in vitro and in vivo evidence, for the first time, that leptin signaling contributes to the invasion and metastasis of pancreatic cancer." (PMID 25948792, 2015). "Addition of the PI3K/AKT inhibitor LY294002 blocked leptin induced migration of pancreatic cancer cells." (PMID 25919692, 2015). "To investigate the in vivo impact of leptin on pancreatic cancer, we established a PANC-1 pancreatic cancer cellline stably overexpressing leptin (PANC-1-Leptin)." (PMID 25948792, 2015). "We further used the MMP-13 inhibitor CL82198 to confirm that leptin's action on the pancreatic cancer cells was mediated by MMP-13." (PMID 25948792, 2015). "In this study, we investigated the role of leptin signaling in pancreatic cancer cells through in vitro and in vivo studies." (PMID 25948792, 2015). "In this study, we found that leptin's functional receptor Ob-Rb was expressed in pancreatic cancer cell lines." (PMID 25948792, 2015). "The overexpression of leptin was shown to significantly promote tumor growth and lymph node metastasis in a subcutaneous model and an orthotopic model of human pancreatic cancer, respectively." (PMID 25948792, 2015).
pancreatic cancer (continued). "The limitation of this study is that we did not simultaneously test the leptin expression using immunohistochemistry in the pancreatic cancer tissues due to the secretory nature of leptin, which makes quantitative analysis a challenge." (PMID 25948792, 2015). "This study suggests leptin signaling as an attractive target for the treatment of pancreatic cancer, especially for patients with metabolic disorders." (PMID 25948792, 2015). "Early studies demonstrated that in vitro treatment of pancreatic cancer cells with low levels of leptin induced a decrease in metabolic activity." (PMID 25919692, 2015). "A possible explanation is that the leptin concentration we and many others have used to treat the cells was 50-100 ng/ml, while in the study showing that leptin inhibited pancreatic cancer cell growth, the authors used 0.4-4 ng/ml of leptin for stimulation." (PMID 25948792, 2015). "Leptin plasma levels are reported to be higher in anorexia nervosa patients, but lower in gastrointestinal, and pancreatic cancer patients." (PMID 20920199, 2010). "At baseline, weight-losing pancreatic cancer patients (n=7) had lower leptin (P<0.05) but higher cortisol, interleukin-6, resting energy expenditure and fat oxidation than healthy subjects (n=6, P<0.05)." (PMID 15026790, 2004). "In pancreatic cancer, leptin (LEP) increases CD133 expression, the number of cells in the S phase, and overall progression and proliferation through increased expression of Notch receptors, ligands, and target molecules (NOTCH1-4, DLL4, JAG1, BIRC5 [survivin], and HEY2)." (PMID 39980929, 2025). "Certain study results of leptin levels in pancreatic cancer are conflicted." (PMID 37444627, 2023). "While leptin enhances pancreatic cancer progression through different signaling pathways, adiponectin may exert a protective effect that is rarely observed with other adipokines." (PMID 37444627, 2023). "Elevated leptin promotes pancreatic tumor invasion and metastasis." (PMID 37444627, 2023). "Through the promotion of angiogenesis by HIF1α, leptin may increase the invasiveness of oral squamous cell carcinoma, gastric cancer cells and pancreatic cancer cells." (PMID 37686525, 2023). "A previous work has also reported that pharmacological activation of adiponectin receptor with AdipoRon could attenuate leptin-induced pancreatic tumor growth through blocking pSTAT3 signaling." (PMID 36361525, 2022). "For example, leptin had antitumoral functions in human pancreatic cancer cell lines." (PMID 34202969, 2021). "In another prospective, nested case-control study, higher leptin levels correlated with an increased risk of pancreatic cancer in men, but not women." (PMID 34680216, 2021). "Results from a large Mendelian randomization study did not support a causal effect of plasma leptin levels on pancreatic cancer development." (PMID 34680216, 2021). "Other studies suggest a correlation between circulating leptin and pancreatic cancer." (PMID 33670492, 2021). "Interestingly, an increased release of leptin from the pancreatic cancer cells was found to modify the tumor microenvironment further by upregulating the expression of leptin receptors in an autocrine/paracrine fashion." (PMID 34588926, 2021). "Although its expression in hepatocellular carcinoma cells is not linked with leptin elicited effects, its expression along with other pancreatic cancer stem cell markers (including Oct-4, CD133, CD24/44 and ALDH) is significantly increased in leptin treated pancreatic cancer cells." (PMID 34588926, 2021). "Higher leptin levels are frequently reported in breast, colon and pancreatic cancers." (PMID 34588926, 2021). "In breast and pancreatic cancer cells, leptin upregulates NOTCH receptors, ligands, and targets." (PMID 32326381, 2020). "However, the roles of circulating leptin and adiponectin in PDAC development remain debatable, as some studies found higher adiponectin/leptin ratios associated with pancreatic cancer." (PMID 31277269, 2019).
pancreatic cancer (continued). "Our study advanced knowledge on dysregulation of adipokines in pancreatic cancer in the context of the sRAGE which showed that sRAGE‐adiponectin and MCP‐PAI1 act differently in pancreatic cancer carcinogenesis, while leptin is involved in both RAGE‐ and MCP1‐related mechanisms." (PMID 29573228, 2018). "Here we investigated in PC cell lines (BxPC-3, MiaPaCa-2, Panc-1, AsPC-1), derived tumorspheres and xenografts whether a functional leptin-Notch axis affects PC progression and expansion of pancreatic cancer stem cells (PCSC)." (PMID 27999190, 2017). "An exception appears to be pancreatic cancer cells where leptin inhibits the growth of Mia-PaCa and PANC-1 pancreatic cancer cells through unknown mechanisms." (PMID 27050378, 2016). "Additionally, the leptin significantly accelerated the invasion of the pancreatic cancer cells through a Matrigel-reconstituted basement membrane matrix towards the bottom chamber." (PMID 25948792, 2015). "Another novel finding of this study is that MMP-13 may play an important role in leptin-induced pancreatic cancer metastasis." (PMID 25948792, 2015). "Edu incorporation assays were performed in order to determine whether leptin effected the proliferation of pancreatic cancer cells." (PMID 25919692, 2015). "Because leptin exerts its biological effects via binding to specific receptors, we first determined whether leptin receptors (Ob-Rs) existed in the human pancreatic cancer cells PANC-1 and AsPC-1." (PMID 25948792, 2015). "In this study, we focused our interests on leptin's effect on pancreatic cancer." (PMID 25948792, 2015). "We next investigated the influence of leptin on the proliferation of human pancreatic cancer cells." (PMID 25948792, 2015). "Taken together, our data suggest that MMP-13 may serve as a downstream effector of the leptin -JAK2/STAT3 cascade responsible for pancreatic cancer cell invasion." (PMID 25948792, 2015). "However, it should be noted that all of the available studies are cross-sectional studies, where the circulating leptin levels were evaluated after the diagnosis of pancreatic cancer." (PMID 25948792, 2015). "As both the migration and invasion of tumor cells contribute to the metastasis of pancreatic cancer, we next addressed whether leptin could influence the migration and invasion potential of human pancreatic cancer cells." (PMID 25948792, 2015). "Application of recombinant leptin to pancreatic cancer cells in vitro resulted in a significant increase in the phosphorylation of AKT,in both the murine Panc02 as well as the human Panc1 suggesting that the short form of the receptor was functional in these cells." (PMID 25919692, 2015). "The increased level of leptin in the plasma as well as the pancreas tissue suggested that leptin might be involved in pancreatic tumor growth." (PMID 25919692, 2015). "Our results suggest that pancreatic cancer cells vary in their responsiveness to leptin." (PMID 25919692, 2015). "To determine whether leptin might additionally act as a migratory factor for pancreatic cancer cells we performed scratch assays." (PMID 25919692, 2015). "Our findings suggest that leptin enhances the invasion of pancreatic cancer through the increase in MMP-13 production, and targeting the leptin/MMP-13 axis could be an attractive therapeutic strategy for pancreatic cancer." (PMID 25948792, 2015). "Although the tumor suppressive effect of rapamycin was thought to be mediated through PI3K/mTOR signaling pathway, our current findings suggest that downregulation of leptin levels may also contribute to the rapamycin-induced pancreatic cancer suppression." (PMID 25948792, 2015). "Leptin, a key adipokine that shows elevated levels in the blood of patients with FP, has been suggested to induce upstream activation of the notch pathway, which is conducive to the increase in tumorigenesis and stimulate the growth of pancreatic cancer stem cell populations." (PMID 40181477, 2025).
pancreatic cancer (continued). "Leptin could impair chemotherapy cytotoxicity and promote chemoresistance in pancreatic cancer." (PMID 37444627, 2023). "Moreover, CAFs are the most abundant cells in the stroma of pancreatic tumors, so it is possible that, in the same way CAFs-secreted leptin could be involved in the invasion of pancreatic cancer cells." (PMID 37686525, 2023). "Moreover, low leptin levels have been correlated with pancreatic cancer." (PMID 34202969, 2021). "Therefore, we performed a nested case–control study within the prospective Women's Health Initiative Study (WHI) to investigate the association between baseline serum concentrations of sRAGE and adiponectin, leptin, MCP1, and PAI1 and incident pancreatic cancer risk." (PMID 29573228, 2018). "However, the biological consequences and molecular mechanisms underlying the activation of the leptin signaling pathway in pancreatic cancer cells have not been investigated in detail." (PMID 25948792, 2015). "However, in one in vitro study, leptin was shown to inhibit the growth of pancreatic cancer cells." (PMID 25948792, 2015). "Therefore, it remains to be determined whether the action of leptin in pancreatic cancer is exerted via an autocrine, paracrine or endocrine mode." (PMID 25948792, 2015). "Therefore, the conclusion that leptin regulates MMP-13 in pancreatic cancer is solid." (PMID 25948792, 2015). "Therefore, we examined whether the JAK/STAT signal pathway is also involved in leptin's action in pancreatic cancer cells." (PMID 25948792, 2015). "Leptin-ObR system is a potent activator of the IL-1 cytokine family in CRC, breast, endometrium and pancreatic cancer cells." (PMID 38152619, 2023). "Leptin can also promote the migration of pancreatic cancer cells by over activating the PI3K/AKT signaling pathway, thus promoting the growth of pancreatic cancer." (PMID 34485124, 2021). "Leptin upregulates the expression of matrix metalloproteinase-13 (MMP-13) through the JAK2/STAT3 signaling pathway and enhances the invasion ability of pancreatic cancer cells." (PMID 34485124, 2021). "Administration of leptin to pancreatic cancer cell lines activates STAT3 signaling, whereas adiponectin inhibits leptin induced phosphorylation of STAT3 in prostate, esophageal and hepatocellular carcinoma cells." (PMID 29156726, 2017). "Leptin signaling via JAK2/STAT3 enhances cell invasion and promotes the metastasis of human pancreatic cancer." (PMID 27036040, 2016). "In vitro, leptin stimulation directly led to the phosphorylation of AKT, which was necessary to confer increased pancreatic cancer cell motility." (PMID 25919692, 2015). "To further understand the relationship between the leptin/MMP-13 axis and human pancreatic cancer development, we performed immunohistochemical staining of Ob-Rb and MMP-13 in 60 pancreatic cancer tissue samples." (PMID 25948792, 2015). "The pooled data revealed that circulating leptin levels were significantly lower in patients with pancreatic cancer than in those without pancreatic cancer or with precancerous lesions." (PMID 37444627, 2023). "Although we did not indicate differences in leptin concentrations in PanNEN patients and management, due to the proven role of leptin in cancerogenesis and pancreatic cancer, further research in more numerous NEN cohorts is required." (PMID 37190276, 2023). "It is also shown that leptin promotes cell invasion and migration through an increase in MMP-13 production, which serves as a downstream effector of the leptin-JAK2/STAT3 cascade responsible for cell invasion in pancreatic cancer cells." (PMID 37686525, 2023). "Leptin treatment upregulates EMT in ovarian and pancreatic cancer cell lines as well." (PMID 37686525, 2023). "Some published data describe ObRs and AdipoRs expression in pancreatic cancer tissues and cell lines, while others report that pancreatic cancer expresses relatively high leptin but not ObRs." (PMID 37444627, 2023).
pancreatic cancer (continued). "Pancreatic cancer patients with cachexia showed a significantly lower leptin level than those without cachexia, while adiponectin levels were conflicting." (PMID 37444627, 2023). "Besides, leptin is reported to induce the expression of Notch1-4, JAG1 and DLL4 in pancreatic cancer cells." (PMID 34588926, 2021). "Another research group further indicated that leptin could promote cancer progression and increase ABCB1 protein synthesis in pancreatic cancer." (PMID 33799880, 2021). "The result from another group further pointed out leptin could induce cancer progression and relative molecule expression including ABCB1 protein in pancreatic cancer." (PMID 29682217, 2018). "Treatment with leptin enhanced the migration and invasion of pancreatic cancer cells but did not affect the proliferation of human pancreatic cancer cells." (PMID 25948792, 2015). "In glioma cells, the up-regulation of MMP-13 by leptin was mediated through p38 MAP kinase and NF-κB pathway, while in pancreatic cancer cells, we found that the expression of MMP-13 was regulated through JAK2/STAT3 signaling pathway in response to leptin stimulation." (PMID 25948792, 2015). "In the present study, we compared the expression levels of MMP-2, MMP-7, MMP-9 and MMP-13 in pancreatic cancer cells with and without leptin treatment." (PMID 25948792, 2015). "To understand whether and which types of MMPs were involved in the pancreatic cancer cell invasion triggered by leptin, we analyzed the expression change of MMP-2, MMP-7, MMP-9 and MMP-13 before and after leptin treatment." (PMID 25948792, 2015). "As for pancreatic cancer, there is a lack of convincing clinical investigations on the relationship between circulating leptin levels and cancer, until now." (PMID 25948792, 2015). "Leptin, through activation of the AKT pathway, may contribute to cell proliferation and glucose metabolism of human pancreatic cells;the leptin–Notch signaling axis is also involved in pancreatic cancer progression." (PMID 37444627, 2023). "The impact of leptin on cancer metastasis has never been investigated in pancreatic cancer." (PMID 25948792, 2015). "The in vivo experiments confirmed that leptin has no inhibitory effect on pancreatic cancer." (PMID 25948792, 2015). "Similarly, in vitro treatment of recombinant leptin to pancreatic cancer cells caused a significant increase in p-Akt in Panc-02 and Panc-1 pancreatic cancer cells, but MiaPaCa-2 cells did not activate p-Akt in response to leptin regarded to the short and long forms of the leptin receptor in cells." (PMID 37529006, 2022).